MICA (MHC class I polypeptide-related sequence A)
Diseases named in the same sentence as MICA in open-access papers (continued):
Sharing a sentence is not in itself a finding about the gene and the disease.
ZIKV infection (1 paper, 2019). "We found that Vδ2 T-cells express high level of NKG2D and, on the other hand, ZIKV infection induced an up-regulation of MICA/B and ULBP2 on target cells, making them more susceptible to NKG2D-mediated lysis." (PMID 31547470, 2019). "Moreover, ZIKV infection was able to increase the expression on A549 cells of NKG2D ligands (NKG2DLs), namely MICA, MICB, and ULBP2, at both the mRNA and protein levels, suggesting the possible involvement of these molecules in the recognition by NKG2D-expressing Vδ2 T-cells." (PMID 31547470, 2019).
tumor (603 papers, 2004 to 2026). "We further explored the association between EHHADH, MICA, and phenotypic markers of macrophages through biostatistical analyses and experimental validation using clinical tumor tissue obtained from HCC patients." (PMID 40723248, 2025). "Chemotherapy can cause tumor cell stress, leading to the upregulation of stress-induced ligands like MICA and MICB, which are recognized by γδT cells." (PMID 40226616, 2025). "The underlying metabolic and molecular mechanisms revealed that MICA in tumor cells induced M2-like polarization through the PPAR/EHHADH pathway, which regulates the fatty acid oxidation (FAO) in macrophages." (PMID 40723248, 2025). "Regarding human NKG2D ligands, in vitro studies have reported that tumor cells expressing MICA, MICB, or ULBP2 are more susceptible to NK cell-mediated cytotoxicity." (PMID 40243581, 2025). "The MICA-129 A/A allele (Met/Met) was associated with the tumor invasion depth of T3/4 in patients with CRC than healthy controls (P = .0261)." (PMID 41431073, 2025). "It promotes the NKG2D‐MICA/B connection by ADCC, thus further enhance susceptibility of MICA/B‐tumor cells to NK cell killing." (PMID 38882209, 2024). "In the tumor microenvironment, proteolytic cleavage of MICA/B by cancer‐associated proteases limits their recognition by effector cells and subsequent tumor cell killing." (PMID 38193112, 2024). "Low expression of MICA/B was associated with large tumor size (p = 0.029) and the risk of portal vein tumor thrombus (PVTT) (p = 0.025)." (PMID 36210637, 2023). "γδ T cells similar to NK and CD8+ T cells interact with MICA/B on tumor cells by expressing NKG2D and causes secretion of perforin proteins and subsequently tumor lysis." (PMID 37605149, 2023). "Post-transcriptional regulation of MICA by miRNAs has been reported in different types of cancer and clinically associated with relevant tumor characteristics and disease progression." (PMID 38146340, 2023). "Shedding of MICA/B facilitates tumour proliferation, as loss of activating ligands on a tumour cell allows immune escape." (PMID 35806034, 2022). "MICA, which is shed from tumor cells, plays a critical role in the immune surveillance against tumor cells and is associated with the prognosis of several malignancies." (PMID 35740916, 2022). "Ma-Mel-86c is positive for the tumour-associated immune ligand MICA while H3122 expresses the epithelial cell marker EpCAM." (PMID 35135541, 2022). "Alternatively, the use of antibodies targeting the site of proteolytic shedding prevents the loss of MICA/B surface expression by human tumor cell lines, inhibiting tumor growth and metastases in humanized mouse models." (PMID 34445750, 2021). "We observed that the majority of patients with the MICA*A9/A6 heterozygote allele showed mainly a poorly differentiated tumor (p = 0.031), indicating that the presence of this genotype is related to an advanced stage of the tumor, as also observed previously." (PMID 33868281, 2021). "Several studies in PC have found that the loss of MICA/B expression from the cell surface and the release of sMIC are associated with a more aggressive tumor phenotype." (PMID 33946818, 2021). "For example, they promote the loss of the NKG2D ligands like MICA/B on tumour cells, possibly through upregulating the expression of ADAM19, a protease responsible for MICA/B cleavage." (PMID 34594338, 2021). "Immune cells expressing NKG2D, such as NK cells and various T-cell subsets, eliminate target cells expressing MICA and other NKG2D ligands, and thus the NKG2D/MICA axis has been implicated in tumor immunosurveillance." (PMID 34683414, 2021). "In HCC, high MICA expression in the tumor microenvironment was associated with increased disease-free and overall survivals, whereas high soluble MICA (sMICA) found in the serum of patients was associated with larger tumor size and reduced overall survival." (PMID 34445750, 2021).
tumor (continued). "MICA is commonly expressed in tumor cells as a tumor-associated antigen that works in tandem with NKG2D receptor to regulate immunosurveillance." (PMID 32528529, 2020). "High expression of MICA and NKG2D is strongly linked to tumor immunosurveillance while low levels of MICA are associated with a poor prognosis in patients receiving aggressive chemotherapy for CRC." (PMID 32528529, 2020). "For example, tumor cells release soluble MICA (sMICA) by proteolytic shedding off from membrane-associated MICA." (PMID 32010486, 2020). "Accordingly, it has been recently demonstrated that antitumor responses by NK cells can be efficiently promoted by antibodies against MICA by blocking MICA/B shedding and coating MICA-expressing tumor cells, rendering them susceptible to ADCC." (PMID 31474977, 2019). "Major histocompatibility complex class I-related gene A (MICA) is a tumor-associated gene containing numerous polymorphisms, which maps to the short arm of human chromosome 6." (PMID 31419949, 2019). "Previous reports from our group and others have shown that the differential mechanisms of NKG2D ligand release are related to the origin of tumor cells and the allelic polymorphisms of MICA." (PMID 30972064, 2019). "Conversely, disruption of the epithelial phenotype during EMT was associated with the loss of the polarized expression of MICA/B, likely rendering tumor cells sensitive to immune elimination." (PMID 30597841, 2018). "In part, these miRNAs were shown to be overexpressed in the tumor itself (“oncomiRs”), like miR-93 that targets both MICA and MICB, but also in metastasis-associated miRNAs (“metastamiRs”), like miR-10b, that targets MICB expression." (PMID 30254634, 2018). "As detailed above, tumor-associated ligands MICA/B and B7-H6 are often found within the peritoneal fluid of serous ovarian cancer patients and impair NK cell effector function." (PMID 29354116, 2017). "Recently, we identified the anti-tumor ligand MHC class I polypeptide-related sequence A (MICA) gene as a susceptibility gene for hepatitis C virus-induced HCC in a genome-wide association study (GWAS)." (PMID 27910927, 2016). "While the mechanisms of tumor immune evasion are not fully understood, the reduction of MICA expression following loss of attachment poises a potential way by which metastasizing tumor cells avoid immune detection." (PMID 28154561, 2016). "mAb04-MICA represents a novel recombinant bispecific antibody-ligand construct in which a fully human IgG1 antibody is used to target tumor cells and the associated MICA stimulates cell killing effect of NK cells." (PMID 26909862, 2016). "We recently performed a genome-wide association study (GWAS) and identified the immunoactivating anti-tumor ligand MHC class I polypeptide-related sequence A (MICA) gene as susceptibility gene for HCV-induced HCC5." (PMID 27910927, 2016). "So far it has been shown that MICA alleles participate in the rejection process of solid organ transplants, immune surveillance of tumours and viruses and the progression of several infectious, inflammatory and autoimmune diseases." (PMID 26672749, 2015). "MICA polymorphism has been associated with a variety of diseases, including inflammatory and autoimmune diseases, infectious and tumor diseases, or even chronic graft-versus-host disease." (PMID 25838620, 2015). "It should be noted that loss of the predominant membrane-bound MICA/B is associated with progression to invasive tumor or to progressively higher grades." (PMID 25228093, 2014). "It is also important to extend our prior work to MICA exon 5 microsatellite polymorphism and evaluate effect modification by age of onset and tumor stage." (PMID 24403192, 2014). "The release of soluble MICA from tumor cells reduces the cell surface density of MICA, leading to reduced susceptibility to NKG2D-mediated cytotoxicity and systemic downregulation of the cell surface expression of NKG2D on effector cells." (PMID 23209462, 2012).
tumor (continued). "Therefore, simply evaluating the intensity of the anti-tumor immune response from the perspective of the amino acid polymorphism of MICA affecting its binding ability to NKG2D also has limitations." (PMID 41594588, 2025). "Conversely, the MICA-129 homozygous allele A/A (Met/Met) variant was related to more advanced clinical characteristics, such as increased tumor invasion depth (T3/4; P = .0261, OR = 2.10), driver gene mutation (P = .0363, OR = 2.65), and KRAS mutation (P = .0392, OR = 2.23)." (PMID 41431073, 2025). "The mesoporous silica rod scaffold vaccine containing polyvalent protein antigen, GM‐CSF, and the adjuvant CpG ODN 1826 resulted in robust generation of MICA/B antibodies, blocking proteolysis of surface‐associated MICA/B and enabling elimination of tumor cells." (PMID 38193112, 2024). "To further explore the pathway enrichment associated with the regulation of tumor immunity by MICA and MMP9, we performed GSEA using the all differentially expressed genes (FDR q-value < 0.05) obtained from the previous analyses in MICA+ HCC cells and MMP9+ macrophages." (PMID 38254761, 2024). "In addition, the NKG2D–ligand interaction can stimulate effector functions in NK cells, eliminate MICA/B-expressing tumor cells through NK cells, and reprogram tumor-associated macrophages (TAMs) into proinflammatory macrophages." (PMID 38791188, 2024). "However, MICA expression should be viewed with caution, because of cleavage susceptibility by metalloproteases expressed by tumor cells." (PMID 38146340, 2023). "Another study analyzed the paired samples from sarcoma patients before and after radiotherapy; the post-radiotherapy tumor cells exhibited stem cell characteristics and an upregulated expression of MICA/B, making them more susceptible to NK cell-mediated cytotoxicity." (PMID 38162672, 2023). "Decreased MICA cell surface expression and increased sMICA levels have been associated with inferior outcome in tumor patients and may represent an important cancer immune evasion principle." (PMID 38035108, 2023). "MiRNAs that have a direct effect on the MICA transcript have been associated with degradation and reduction of MICA expression on the tumor cell membrane, which may affect the cytotoxic response mediated by NK cells." (PMID 38146340, 2023). "Moreover, CAR-NK cell injected tumor regions showed loss of expression of the NKG2D ligands MICA/B, Villin and CDX2 (markers of adenocarcinoma of intestinal origin), supporting the argument of local antitumor effect in the patients." (PMID 35242135, 2022). "Importantly, EVs from cytokine-stimulated NK cells penetrate into the spheroid core, and tumor spheroid susceptibility to NK-cell derived EVs was linked to differential expression of the NKG2D ligands MICA/B, which was blocked with an anti-NKG2D antibody." (PMID 35119498, 2022). "This probably reflects that certain MICA alleles are preferentially recruited to EVs while others are not, which could depend on allelic differences or metabolic state of the tumour." (PMID 36726591, 2022). "Apart from the vast range of MICA polymorphisms, dysregulation of MICA expression in tumor cells might also help the later to evade immune-mediated cytotoxicity." (PMID 34943820, 2021). "In this scenario, the most frequent MICA allele *008 is released from tumor cells in association with EVs and treatment of NK cells with MICA*008+ EVs induced the downregulation of NKG2D from the cell surface and decreased NK cell cytotoxicity independent of NKG2D ligand expression on target cells." (PMID 35003134, 2021). "MICA expression rendered B16F10-MICA cells strongly susceptible to cytolysis by purified splenic NK cells from both nontgLM and MICAgen mice, but not from NKG2D-deficient mice, demonstrating unimpaired NKG2D-mediated immunorecognition of tumor-associated human MICA by MICAgen NK cells." (PMID 32582150, 2020).
tumor (continued). "In agreement with the previous report, our study show that anti-MICA specific antibody could strongly inhibit the loss of MICA from the tumor membrane surface and substantially increase the expression of MICA/B." (PMID 32645836, 2020). "Furthermore, the production of tumor-derived exosomes containing MICA/B and FasL is associated with impairment of the effectives of both innate and adaptive immunity." (PMID 29515996, 2018). "Finally, we sought to address a functional “cross-tolerance” of CD3ζ-associated NKp46 in H2-Kb-MICA mice in a tumor rejection experiment." (PMID 29163533, 2017). "The mechanism underlying the enhanced tumor cell killing may involve the increased expression of MICA, MICB, PVR, and Nectin-2 proteins on MM cells and the ligands of the activating receptors, NKG2D and DNAM-1." (PMID 27992381, 2017). "However, progressive stages of cancer are associated with tumor shedding of MICA/B, which appears to systemically impair the immunological competence of individuals with cancer by causing downregulation of NKG2D." (PMID 29354116, 2017). "Notably, these BRAF-mutated tumor cells express the NKG2D ligands MICA/B at a higher level than unmutated tumors as a consequence of the activation of the MAPK pathway." (PMID 27563819, 2016). "The association between serum MICA levels with different tumor stages was also determined." (PMID 21605422, 2011). "We suspect that the length of MICA transmembrane region, relative to the presence of six or more alanine residues, could implicate an increased susceptibility for proteolytic shedding of MICA by metalloproteases in the tumor microenvironment." (PMID 33868281, 2021). "In addition to its intrinsic activity associated with NKG2D, MICA may also serve as a tumor-antigen for antibody-dependent cellular cytotoxicity (ADCC)." (PMID 31387641, 2019). "Reduced MICA expression upon loss of attachment or increased cell–cell contact results in reduced susceptibility to NK cell killing, suggesting a mechanism whereby metastasizing tumor cells may evade immune recognition." (PMID 28154561, 2016). "7C6-GAALIE inhibits MICA/B shedding and potently triggers NK cell-effector functions against tumor cells." (PMID 41999749, 2026). "In summary, the expression of MICA in tumor cells leads to the infiltration of M1-like macrophages in early-stage HCC in co-culture models." (PMID 40723248, 2025). "The shedding of NKG2DLs, mediated by tumor-secreted metalloproteases or the release of NKG2DLs via exosomes, leads to soluble MICA/B that can bind to NKG2D receptors thereby impairing the effector functions of NK and T cell that rely on NKG2D signaling." (PMID 40013140, 2025). "For clarification, 7C6-hIgG1 binds to and inhibits the shedding of major histocompatibility complex class I polypeptide-related sequence A and B (MICA/B), which are surface proteins expressed by tumor cells in response to stress pathways." (PMID 41219228, 2025). "NK cells recognize the MicA molecule on target tumor cells using the NKG2D receptor and kill them with the aid of granzymes." (PMID 40362307, 2025). "They exhibit elevated expression of CD16 and NKG2D receptors, which are capable of identifying stress ligands on tumor cells (such as MICA/B) and function synergistically with CD8+ T cells to eradicate immuno-evasive tumor cells." (PMID 41409300, 2025). "MICA proteins are expressed at low levels on the surface of normal cells but are highly expressed on the surface of tumor cells." (PMID 41594588, 2025). "Tumor cells can evade immune surveillance by degrading MICA, leading to its internalization by NK cells via NKG2D, thereby silencing NK cell responses." (PMID 39751938, 2025). "These metalloproteinases hydrolyze MICA and other ligands on the surface of tumor cells to generate soluble molecules." (PMID 40563539, 2025). "The abnormally high expression of these two signaling pathways in tumors leads to the massive shedding of ligands such as MICA, which is conducive to tumor progression." (PMID 40563539, 2025).